C5AR2 (complement C5a receptor 2)
Description:
Receptor for the chemotactic and inflammatory peptide anaphylatoxin C5a, stimulating chemotaxis, granule enzyme release, intracellular calcium release and superoxide anion production. Also acts as a receptor for dearginated forms of C3a, C4a and C5a anaphylatoxin peptides (ASP/C3adesArg, C4adesArg and C5adesArg, respectively). Ligand binding causes a conformation change that triggers signaling via guanine nucleotide-binding proteins (G proteins) and modulates the activity of downstream effectors, such as adenylate cyclase. C5AR1 is coupled to G(i)/G(o) (GNAI1 or GNAO1) G alpha proteins and mediates inhibition of adenylate cyclase.
Synonyms: C5L2; GPR77; GPF77
Tractability: Small molecule: it belongs to a druggable protein family. Antibody: UniProt places it where antibodies can reach, with high confidence; its Gene Ontology location is reachable by antibodies, with high confidence; UniProt predicts a signal peptide or a membrane-spanning region. PROTAC: a small molecule that binds it is known.
Target class: Family A G protein-coupled receptor; Anaphylatoxin receptor family; Membrane receptor; Anaphylatoxin receptor; Peptide receptor (family A GPCR)
Gene: Protein-coding gene on chromosome 19 (47,332,148 to 47,347,329, forward strand). Ensembl gene ENSG00000134830.
Subcellular location: Cell membrane
Pathways (Reactome):
Immune System: Regulation of Complement cascade
Signal Transduction: Peptide ligand-binding receptors
Gene Ontology:
Molecular function: protein binding; complement component C5a receptor activity; G protein-coupled receptor activity; complement receptor activity
Biological process: negative regulation of interleukin-6 production; negative regulation of neutrophil chemotaxis; negative regulation of tumor necrosis factor production; regulation of interleukin-8 production; complement receptor mediated signaling pathway; inflammatory response; phospholipase C-activating G protein-coupled receptor signaling pathway; positive regulation of cytosolic calcium ion concentration; chemotaxis; complement component C5a signaling pathway; G protein-coupled receptor signaling pathway; regulation of immune system process
Cellular component: apical part of cell; basal plasma membrane; plasma membrane; basolateral plasma membrane; membrane
Genetic constraint (gnomAD): Loss-of-function variants: 0 observed, 0.74 expected, observed/expected ratio (o/e) 0, 90% interval 0 to 1.79. That is too few expected variants to judge how well the gene tolerates losing a copy. Missense variants: 458 observed, 458.62 expected, observed/expected ratio (o/e) 1, 90% interval 0.92 to 1.08. Synonymous variants: 224 observed, 213.69 expected, observed/expected ratio (o/e) 1.05, 90% interval 0.94 to 1.17.
Homologues: Orthologues: chimpanzee C5AR2 (98% identical), macaque C5AR2 (93% identical), pig C5AR2 (77% identical), dog C5AR2 (74% identical), guinea pig C5AR2 (71% identical), rabbit C5AR2 (66% identical), mouse C5ar2 (62% identical), rat C5ar2 (60% identical), tropical clawed frog c5ar1 (31% identical), zebrafish c5ar1 (30% identical). Paralogues in human: C5AR1 (36% identical), C3AR1 (30% identical), CMKLR1 (28% identical), FPR2 (27% identical), FPR1 (27% identical), FPR3 (25% identical), GPR32 (23% identical), GPR33 (20% identical).
Diseases named in the same sentence as C5AR2 in open-access papers:
C5AR2 is named in the same sentence as 84 diseases in open-access papers, as found by Europe PMC text mining. Sharing a sentence is not in itself a finding about the gene and the disease. The quoted sentences say what the papers report.
Sepsis (31 papers, 2008 to 2025). Sepsis is defined as life-threatening organ dysfunction caused by a dysregulated host response to infection. "Meanwhile, in mouse models of cecal ligation and puncture-induced sepsis, either C5aR1 or C5aR2 deficiency was protective, reflected in improved survival outcomes or better cardiac functions." (PMID 39021433, 2024). "In cardiomyocyts (CMs) from CLP-septic C5aR1 and C5aR2 KO mice, both receptors contributed to the cytokine storm that have been linked to cardiosuppression in sepsis, demonstrated by reduced levels of IL-6, TNFα, IL-1β, IL-10, and others." (PMID 28706957, 2017). "In sepsis blockade of either C5aR 1, C5aR2 or C5a were associated with decreased serum levels of IL-6." (PMID 27437704, 2016). "However, it was reported that C5aR2 in blood neutrophils was associated with poor prognosis of sepsis both in humans and rat models." (PMID 39021433, 2024). "Depending on disease models studied, or even in the same disease studied by different groups or from different perspectives, C5aR2 functions either as pro- and/or anti-inflammatory mediators, such as in sepsis and allergic asthma." (PMID 39021433, 2024). "The pro-inflammatory roles of C5aR2 and its partner C5aR1—the classical receptor for C5a have been shown in several experimental disease models using C5ar1-/- and C5ar2-/- mice, for example, atherosclerosis, renal ischemic reperfusion injury, and sepsis." (PMID 39021433, 2024). "Our studies of polymicrobial sepsis have highlighted the role of complement activation products (especially C5a anaphylatoxin and its receptors C5aR1 and C5aR2) in adverse effects of sepsis." (PMID 33425963, 2020). "During the inflammatory condition of CLP-sepsis, C5a-C5aR2 interactions were shown to induce excessive amount of cytosolic ROS and [Cai2+] in CMs." (PMID 32117238, 2020). "Considering the small differences between sepsis outcome after blockade of C5aR1 alone (PMX205) versus C5aR1 plus C5aR2 (A8Δ71−73), the additional effect of blocking C5aR2 seems to be minor." (PMID 31274379, 2019). "C5aR2 was also involved in the production of G-CSF in a mouse model of polymicrobial sepsis, which was characterized by acute inflammation." (PMID 31011487, 2019). "Here, we aimed to extend our analyses to the relative contributions of all three anaphylatoxin receptors, C3aR, C5aR1 and C5aR2 to meningococcal nasopharyngeal colonization as well as sepsis pathology using in vivo and ex vivo models of disease." (PMID 31274379, 2019). "Unfortunately, no specific C5aR2 inhibitor is available to individually assess the role of C5aR2 during Nme sepsis." (PMID 31274379, 2019). "In CLP-driven sepsis, for example, only the combined inhibition of C5aR1 and C5aR2 improves animal survival." (PMID 29520270, 2018). "In experimental CLP-sepsis complement C5a receptor 1 knock out (C5aR1-/-) and C5a receptor 2 knock out (C5aR2-/-) mice had superior survival rates compared to wt." (PMID 27437704, 2016). "Thus, we expanded upon our recent observation that C5aR1 aggravates Nme sepsis pathophysiology in showing that C3aR is protective, whereas C5aR2, like C5aR1, is detrimental in the mouse Nme sepsis model." (PMID 31274379, 2019). "And whether the regulation and function of C5aR2 in different organs in sepsis are similar to those in myeloid cells remains to be defined." (PMID 28706957, 2017). "There is a C5aR2-dependent upregulation of HMGB1 in sepsis both in vivo and in vitro, while in the context of cerebral malaria induced by Plasmodium falciparum it is C5aR1, but not C5aR2, that causes the elevated plasma HMGB1." (PMID 28706957, 2017). "Surface C5aR2 on neutrophils and peritoneal macrophages maintained by sphingosine kinase 1-sphingosine-1-phosphate (Sphk1-S1P) interaction dampened inflammation in endotoxin-induced sepsis in mice, in part through ERK1/2." (PMID 28706957, 2017). "The surface levels of C5aR2 on mouse and rat neutrophils may play a vital role in sepsis." (PMID 28706957, 2017).
Sepsis (continued). "However, research on blood neutrophils in experimental and clinical sepsis showed that the downregulation of C5aR2 levels in PMNs demonstrated by western blot and flow cytometry was associated with a poor prognosis, indicating the protective role of C5aR2 in counterbalancing C5aR1." (PMID 28706957, 2017). "In murine models of LPS-induced sepsis and OVA-sensitized allergic asthma, pulmonary expression levels of the complement anaphylatoxin receptors C3aR, C5aR1, and C5aR2 were markedly elevated." (PMID 40963601, 2025). "Absence of either C5aR1 or C5aR2 attenuates cardiac dysfunction and improves survival of mice during sepsis." (PMID 32117238, 2020). "In contrast, the absence of C5aR2 led to reduced inflammation in models of air pouch, acute lung injury, sepsis and renal ischemia-reperfusion injury in mice." (PMID 31011487, 2019). "In sepsis, C5aR2, not C5aR1, was responsible for the release of HMGB1, which was supported by an observation made by Croker and colleagues that high mobility group bow-1 (HMGB1) production from macrophages was independent on C5aR1-C5aR2 heteromer." (PMID 28706957, 2017). "Absence of either C5aR1 or C5aR2 was protective for heart function during sepsis." (PMID 32410859, 2020). "Proinflammatory properties of C5aR2 have been shown in experimental allergic asthma, dextran sulfate sodium- (DSS-) induced acute colitis, thioglycollate-induced peritonitis and air-pouch inflammation, acute lung injury (AKI), acute pyelonephritis, renal I/R injury, and sepsis." (PMID 28706957, 2017).
breast carcinoma (29 papers, 2018 to 2025). "In oncology, the role of C5aR2 remains controversial with links to immune infiltration, macrophage polarisation, and regulation of tumourigenic pathways in breast cancer and a protective association in a murine model of melanoma." (PMID 38067135, 2023). "In this study, we noticed that C5AR2 was involved in the polarization of macrophages, and C5AR2 expression was positively associated with M2 macrophages and negatively with M1 macrophages in breast cancer." (PMID 34595119, 2021). "In summary, our present study provides insights into the malignant properties of C5AR2 and its potential role in tumor immunology, suggesting that C5AR2 can stand as a prospective biomarker in breast cancer." (PMID 34595119, 2021). "Otherwise, CCK8 assay and Transwell assay were conducted to illustrate the role of C5AR2 in migration, invasion, and proliferation of breast cancer cells." (PMID 34595119, 2021). "The results also showed higher C5AR2 expression level in the breast cancer tissues than the paired adjacent tissues." (PMID 34595119, 2021). "C5AR2 overexpression facilitated the functions such as migration, invasion, and proliferation in breast cancer cells, which is consistent with bioinformatics analysis." (PMID 34595119, 2021). "Overall, C5AR2 promotes the proliferation, migration, invasion, and activation of oncogenic pathways in breast cancer cells." (PMID 34595119, 2021). "C5AR2: C5AR2 is involved in immune infiltration and malignant characteristics of breast cancer, which may be a prospective biomarker for breast cancer." (PMID 37468832, 2023). "C5AR2 is involved in immune infiltration and malignant characteristics of breast cancer, which may be a prospective biomarker for breast cancer." (PMID 34595119, 2021). "Moreover, C5AR2 expression levels were dramatically correlated with recognized immune infiltration, especially the polarization of macrophages in breast cancer." (PMID 34595119, 2021). "Notably, C5AR2 expression levels were diverse in subtypes of breast cancer, and it was much higher in Lumina A and Lumina B (ER-positive) than in HER2 and Basal (ER-negative) in the TIMER2.0 database." (PMID 34595119, 2021). "This present study may provide novel insights to show the potential of C5AR2 in breast cancer therapy." (PMID 34595119, 2021). "In addition, the relationships of C5AR2 to other classic genes in key signaling pathways in breast cancer were analyzed through the TIMER database." (PMID 34595119, 2021). "Notably, in breast cancer, C5AR2 expression levels were positively related to immune infiltration of M2 macrophages while negatively related to M0 and M1 macrophages." (PMID 34595119, 2021). "Besides, transwell assay was performed, and the results revealed that C5AR2 overexpression also significantly enhanced the migratory and invasive capacity of breast cancer cells." (PMID 34595119, 2021). "Strong correlations were shown between elevated C5AR2 expression and poorer prognosis in BRCA (ER-positive), indicating that C5AR2 has a malignant biological character as well as specific prognostic value, and it may be an oncogene in breast cancer." (PMID 34595119, 2021). "However, research of C5AR2 in cancer is limited, and its function remains unclear in breast cancer." (PMID 34595119, 2021). "To explore how C5AR2 affects the proliferation of breast cancer cells, we overexpressed C5AR2 in MDA-MB-231 cells and validated the success of C5AR2 overexpression in this cell line." (PMID 34595119, 2021). "However, the function and mechanism of C5AR2 independent of complement system in breast cancer remains unknown." (PMID 34595119, 2021).
Obesity (8 papers, 2010 to 2025). Accumulation of substantial excess body fat. "Macrophage infiltration in adipose tissue and diverse cytokines in plasma were all elevated in C5aR2 KO mice on a fat-enriched diet, which coincided with the chronic low-grade inflammatory state in obesity-associated disorders." (PMID 28706957, 2017). "The involvement of C5aR2 in obesity and related pathologies has long been reported and summarized in detail in several reviews." (PMID 28706957, 2017). "The binding of ASP to C5aR2 is still in debate, albeit animal and clinical data supporting the involvement of both in obesity and in metabolism." (PMID 28706957, 2017).
allergic asthma (6 papers, 2017 to 2025). A asthma with a basis in a pathological type I hypersensitivity reaction. "In two models of OVA- and house dust mite- (HDM-) induced allergic asthma, C5aR2 deficiency was protective, with reduced airway hyperresponsiveness and Th2 cytokine production." (PMID 28706957, 2017). "C5a regulates the development of experimental allergic asthma during allergen sensitization and the effector phase through activation of its two cognate receptors C5aR1 and C5aR2." (PMID 28231307, 2017). "C5aR1 exerts a proinflammatory role in several autoimmune diseases, whereas the role of C5aR2 is still enigmatic, with both immune-activating and immunosuppressive functions in inflammatory disease models such as allergic contact dermatitis and allergic asthma." (PMID 36466856, 2022).
allergic contact dermatitis (4 papers, 2017 to 2025). An inflammatory skin condition caused by an immune response to direct contact between the skin and an allergen. "On the contrary, in allergic contact dermatitis and LPS- and immune complex- induced lung injury, C5aR2 deficiency exacerbates inflammation and tissue injury in mice, providing evidence for the anti-inflammatory role of C5aR2." (PMID 28706957, 2017).
diabetes (4 papers, 2015 to 2025). "The fact that c5ar2 SNPs are associated with metabolic dysregulation, including cardiovascular disease and diabetes, may indicate a role for the receptor in diabetic complications, including DKD." (PMID 37240105, 2023). "In this study, we found that valproic acid also attenuated diabetes-induced upregulation of complement genes, such as C5aR1 and C5aR2, in the diabetic kidney, suggesting a new pathway regulated by valproic acid." (PMID 36434087, 2022). "C5aR2 has also been reported to be strongly expressed on human plaques in the chronic inflammatory condition atherosclerosis, a common comorbidity of diabetes." (PMID 37240105, 2023). "Furthermore, valproic acid attenuated diabetes-induced upregulation of C5ar1 and C5ar2 expression, concomitant with a downregulation of cellular senescence markers." (PMID 36434087, 2022).
glomerulonephritis (4 papers, 2012 to 2020). A renal disorder characterized by damage in the glomeruli. "Similarly, C5aR1 is expressed scarcely, whereas expression of C5aR2 is upregulated in MPO-ANCA+ glomerulonephritis." (PMID 29686675, 2018). "Avacopan does not interfere with the production of C5b or the membrane attack complex (ie, terminal complement complex) and does not block C5a binding to a second receptor, C5L2 (also called C5aR2), shown to be protective in antimyeloperoxidase glomerulonephritis." (PMID 32088663, 2020). "Importantly, avacopan does not inhibit the interaction of C5a with the related receptor C5L2 (also referred to as C5aR2), thought to have anti-inflammatory properties and also shown to impart protective effects in a mouse model of anti-MPO-induced glomerulonephritis." (PMID 32088663, 2020). "However, in the murine model of MPO-ANCA-induced glomerulonephritis, blocking of C5aR1 with a small molecule antagonist (avacopan) is protective, whereas lack of C5aR2 lead to aggravated disease." (PMID 29686675, 2018).
hyperlipidemia (4 papers, 2014 to 2017). "C5aR2 gene single nucleotide polymorphisms were found to be associated with metabolic disorders in different populations, including hyperlipidemia, T2DM, and coronary heart disease." (PMID 28706957, 2017). "The S323I (Ser to Ile) mutation in the Ser-Thr rich carboxyl terminal of C5aR2 was found to be associated with a familial combined hyperlipidemia, probably due to the loss of function by this mutant in mediating ASP-induced signaling." (PMID 28706957, 2017).
Insulin resistance (4 papers, 2012 to 2025). Increased resistance towards insulin, that is, diminished effectiveness of insulin in reducing blood glucose levels. "Furthermore, adipocytes express C3aR and C5aRs (C5aR1 and C5aR2), which, via their corresponding ligands (C3a and C5a), increase the local and systemic inflammation along with increasing insulin resistance." (PMID 40904461, 2025).
melanoma (4 papers, 2020 to 2025). A malignant, usually aggressive tumor composed of atypical, neoplastic melanocytes. "In consistent with a previous report in a melanoma bearing murine model 42, we showed that in contrast to C5aR1, C5aR2 deficiency accelerated tumor development, suggesting an anti-inflammatory role of C5aR2 in AOM/DSS-induced CRC tumorigenesis." (PMID 32754267, 2020).
Alzheimer disease (3 papers, 2022 to 2025). A progressive, neurodegenerative disease characterized by loss of function and death of nerve cells in several areas of the brain leading to loss of cognitive function such as memory and language. "Other IFN-related conditions, such as STING-associated vasculopathy with onset in infancy (SAVI) and tauopathies, including Alzheimer’s disease, both linked to dysregulated Type I IFN responses, warranting further research of C5aR2 in these contexts." (PMID 38067135, 2023).
Arthritis (3 papers, 2010 to 2024). Inflammation of a joint. "And recently, a new discovery about C5aR2 function revealed that C5aR2 on endothelium transported C5a generated in the arthritic joint to the blood vessel lumen to initiate C5aR1-driven neutrophil arrest, in a mouse model of immune complex-induced arthritis." (PMID 39021433, 2024). "C5aR2 has also been implicated in inflammatory processes, including NLRP3 inflammasome regulation in macrophages and regulation of neutrophilic inflammation in epidermolysis bullosa acquisita and arthritis." (PMID 38067135, 2023).
autoimmune disease (3 papers, 2020 to 2023). A disorder resulting from loss of function or tissue destruction of an organ or multiple organs, arising from humoral or cellular immune responses of the individual to their own tissue constituents. "Using mice with a global deficiency of C5aR2, we have previously reported an important role of this receptor in the pathogenesis of the neutrophil-driven autoimmune disease epidermolysis bullosa acquisita (EBA)." (PMID 37275893, 2023). "This underscores the importance of C5aR2 in the pathogenesis of neutrophil-mediated autoimmune diseases." (PMID 37275893, 2023). "In summary, the findings presented here confirm our previous hypothesis that C5aR2 plays a critical role in regulating neutrophil activation and function that contributes to neutrophil-driven autoimmune diseases such as EBA." (PMID 37275893, 2023).